ATP6V1F (ATPase H+ transporting V1 subunit F)
Description:
Subunit of the V1 complex of vacuolar(H+)-ATPase (V-ATPase), a multisubunit enzyme composed of a peripheral complex (V1) that hydrolyzes ATP and a membrane integral complex (V0) that translocates protons. V-ATPase is responsible for acidifying and maintaining the pH of intracellular compartments and in some cell types, is targeted to the plasma membrane, where it promotes acidification of the extracellular environment (By similarity). The V-ATPase complex also acts as an activator for mTORC1 on lysosomal membrane by promoting the guanine nucleotide exchange factor (GEF) of the Ragulator complex, thereby enabling mTORC1 recruitment.
Synonyms: ATP6S14; VATF; Vma7
Tractability: Small molecule: a structure with a bound ligand is known. Antibody: UniProt places it where antibodies can reach, with high confidence. PROTAC: ubiquitination databases record sites on it; its protein half-life has been measured.
Gene: Protein-coding gene on chromosome 7 (128,862,856 to 128,865,847, forward strand). Ensembl gene ENSG00000128524.
Subcellular location: Cytoplasmic vesicle, secretory vesicle, synaptic vesicle membrane; Cytoplasmic vesicle, clathrin-coated vesicle membrane
Pathways (Reactome):
Transport of small molecules: Ion channel transport; Transferrin endocytosis and recycling
Cellular responses to stimuli: Amino acids regulate mTORC1
Developmental Biology: Regulation of MITF-M-dependent genes involved in lysosome biogenesis and autophagy
Immune System: ROS and RNS production in phagocytes
Signal Transduction: Insulin receptor recycling
Gene Ontology:
Molecular function: protein binding; ATPase-coupled ion transmembrane transporter activity; proton transmembrane transporter activity; proton-transporting ATPase activity, rotational mechanism
Biological process: endosomal lumen acidification; Golgi lumen acidification; intracellular pH reduction; lysosomal lumen acidification; proton transmembrane transport; vacuolar acidification; monoatomic ion transmembrane transport; synaptic vesicle lumen acidification
Cellular component: extracellular exosome; membrane; vacuolar proton-transporting V-type ATPase complex; cytosol; endosome membrane; Golgi membrane; lysosomal membrane; plasma membrane; proton-transporting V-type ATPase complex; vacuolar proton-transporting V-type ATPase, V1 domain; clathrin-coated vesicle membrane; proton-transporting V-type ATPase, V1 domain; synaptic vesicle membrane
Genetic constraint (gnomAD): Loss-of-function variants: 4 observed, 7.06 expected, observed/expected ratio (o/e) 0.57, 90% interval 0.28 to 1.29. That is too few expected variants to judge how well the gene tolerates losing a copy. Missense variants: 136 observed, 173.23 expected, observed/expected ratio (o/e) 0.79, 90% interval 0.68 to 0.9. Synonymous variants: 68 observed, 70.48 expected, observed/expected ratio (o/e) 0.96, 90% interval 0.79 to 1.18.
Homologues: Orthologues: chimpanzee ATP6V1F (100% identical), dog ATP6V1F (98% identical), guinea pig ATP6V1F (98% identical), macaque ATP6V1F (98% identical), mouse Atp6v1f (98% identical), pig ATP6V1F (97% identical), rabbit ATP6V1F (97% identical), tropical clawed frog atp6v1f (87% identical), zebrafish atp6v1f (83% identical), rat Ang (82% identical), Caenorhabditis elegans vha-9 (70% identical), Drosophila melanogaster Vha14-2 (43% identical).
Diseases named in the same sentence as ATP6V1F in open-access papers:
ATP6V1F is named in the same sentence as 20 diseases in open-access papers, as found by Europe PMC text mining. Sharing a sentence is not in itself a finding about the gene and the disease. The quoted sentences say what the papers report.
colorectal cancer (2 papers, 2021 to 2022). A primary or metastatic malignant neoplasm that affects the colon or rectum. "Consistent with our results, ATP6V1F, PPP1R14B and SLC7A5 were reported to play oncogenic roles in colorectal cancer progression." (PMID 36620589, 2022). "The results showed that only four genes, including ATP6V1F, PPP1R14B, BTF3L4 and SLC7A5, were oncogenes that are required for cell proliferation of stomach cancer, liver cancer and colorectal cancer." (PMID 36620589, 2022). "The gene expression correlation analysis showed that miR-194 expression showed a negative correlation with the expression of ATP6V1F, PPP1R14B, BTF3L4 and SLC7A5 in gastric cancer, liver cancer and colorectal cancer." (PMID 36620589, 2022).
hepatocellular carcinoma (2 papers, 2023 to 2025). A malignant tumor that arises from hepatocytes. "ATP6V1F is overexpressed in hepatocellular carcinoma (HCC), and this overexpression is associated with poor prognosis, immune cell infiltration, and elevated expression of immune checkpoints." (PMID 39857726, 2025).
rectal cancer (2 papers, 2020 to 2025). A primary or metastatic malignant neoplasm that affects the rectum. "Comparatively, SNHG1 was found to promote initiation and metastasis of rectal cancer through regulating let-7b-5p/ATP6V1F and miR-423-5p/EZH2 axes, respectively." (PMID 33194594, 2020).
Anxiety (1 paper, 2021). Intense feelings of nervousness, tension, or panic often arise in response to interpersonal stresses. "The results indicated that Atp6v1f, Arpc5, Adcyap1r1, Ndufb6, and Psmc6 were distinctly dysregulated in the hypothalamus of the depression-susceptible group, while Gys1, Pgp, Klc1, Chka, Ncstn, Ndufa6, and Kyat1 were distinctly dysregulated in the anxiety-susceptible group." (PMID 33737865, 2021).
COVID-19 (1 paper, 2022). A disease caused by infection with severe acute respiratory syndrome coronavirus 2. "Similarly, the ATP6V0C (c subunit) and ATP6V1F (F subunit) of V-ATPase also showed cell type-specific expression levels in moderate/severe COVID-19 patients." (PMID 35974012, 2022).
depression (1 paper, 2021). "The expressions of Atp6v1f, Arpc5, Ndufb6, and Psmc6 were significantly down-regulated while Adcyap1r1 was up-regulated in the depression-susceptible group compared with the control group." (PMID 33737865, 2021).
lysosomal disorders (1 paper, 2023). "Here, we found that lysosomal channel proteins (ATP6V0B, ATP6V1E1, ATP6V0D1, ATP6V1F) were significantly decreased in AD, which may mediate the elevation of lysosomal pH leading to lysosomal disorders." (PMID 37334737, 2023).
tumor (7 papers, 2020 to 2026). "Protein profiling identified ITH-associated proteins (WDR5, CKB, IPO11, ATP6V1F, DCXR and PCCB) and underscored pathway variations including tumour suppressor and proto-oncogenic signalling, vascularization and metabolic regulation." (PMID 41580526, 2026). "Our finding highlights that miR-194 exerts a tumor-suppressive role in digestive system cancers by targeting ATP6V1F, PPP1R14B, BTF3L4 and SLC7A5." (PMID 36620589, 2022). "Transcriptome sequencing and Genome-wide CRISPR/Cas9 proliferation screening confirmed that miR-194 play tumor suppressive roles in GIC mainly by targeting ATP6V1F, BTF3L4, PPP1R14B and SLC7A5." (PMID 36620589, 2022). "The results showed that the mRNA expressions of ATP6V1D, ATP6V1F, and ATP6V1F were obviously related to tumor purity." (PMID 33194650, 2020). "In these ceRNA triplets, miR-484, miR-181a-5p, miR-423-5p and let-7b-5p were identified as miRNA biomarkers with excellent distinguishing ability between normal and tumor tissues, and ANKRD36, PCGF2, EZH2 and ATP6V1F were closely related to the prognosis of corresponding cancer." (PMID 33194594, 2020).
cancer (3 papers, 2020 to 2026). A tumor composed of atypical neoplastic, often pleomorphic cells that invade other tissues. "ATP6V1F is often regarded as an immunotherapeutic target for cancers and can regulate cancer progression by activating immune-related pathways." (PMID 40727388, 2025).
infection (3 papers, 2020 to 2025). The state of being infected such as from the introduction of a foreign agent such as serum, vaccine, antigenic substance or organism. "Ferritin heavy chain 1 (FTH1), ferritin light chain (FTL), mitochondrial ferritin (FTMT), and ATP6V1F were the downregulated genes identified in A. baumannii without resistant gene infection-associated pulmonary host response." (PMID 39857726, 2025).
ATP6V1F also shares sentences with these, for which no sentence is quoted: candidiasis (2 papers); colon cancer (2); digestive system cancer (1); gastric cancer (1); leukemia (1); liver cancer (1); lung adenocarcinoma (1); nasopharyngeal carcinoma (1); prostate carcinoma (1); stomach cancer (1).